Y_RNA (Y RNA )
Gene: Miscellaneous RNA gene on chromosome X (11,116,092 to 11,116,193, reverse strand). Ensembl gene ENSG00000207151.
Homologues: Orthologues: chimpanzee Y_RNA (98% identical), macaque Y_RNA (94% identical), guinea pig Y_RNA (90% identical), guinea pig Y_RNA (87% identical). Paralogues in human: Y_RNA (92% identical), RNY3 (91% identical), Y_RNA (91% identical), RNY3P1 (90% identical), Y_RNA (90% identical), Y_RNA (89% identical), Y_RNA (88% identical), Y_RNA (87% identical), Y_RNA (86% identical), RNY3P11 (85% identical), RNY3P14 (85% identical), RNY3P5 (85% identical), and 97 more.